RN7SL668P (RNA, 7SL, cytoplasmic 668, pseudogene)
Gene: Miscellaneous RNA gene on chromosome 1 (234,904,186 to 234,904,488, forward strand). Ensembl gene ENSG00000239690.
Homologues: Orthologues: chimpanzee Metazoa_SRP (99% identical), macaque Metazoa_SRP (92% identical). Paralogues in human: RN7SL1 (83% identical), RN7SL2 (82% identical), RN7SL3 (80% identical), RN7SL7P (79% identical), RN7SL60P (79% identical), RN7SL732P (78% identical), RN7SL296P (78% identical), RN7SL828P (78% identical), RN7SL664P (77% identical), RN7SL709P (77% identical), RN7SL408P (77% identical), RN7SL126P (77% identical), and 699 more.
Diseases named in the same sentence as RN7SL668P in open-access papers:
RN7SL668P is named in the same sentence as 2 diseases in open-access papers, as found by Europe PMC text mining. Sharing a sentence is not in itself a finding about the gene and the disease.
RN7SL668P shares sentences with these, for which no sentence is quoted: cancer (1 paper); tumour (1).